CD47 (CD47 molecule)
Diseases named in the same sentence as CD47 in open-access papers (continued):
Sharing a sentence is not in itself a finding about the gene and the disease.
tumor (continued). "In addition, the expression of CD47 on normal tissues may create an ‘antigen sink’ that prevents anti-CD47 therapeutic antibodies from reaching tumor cell targets in vivo, which also pose a problem in the development of anti-CD47 bsAbs." (PMID 34305918, 2021). "Thus, the blockade of the CD47–SIRPα interaction by anti-CD47 antibody could restore the macrophage-mediated phagocytosis against tumor." (PMID 34675914, 2021). "Moreover, HT enhanced the anti-tumor effect of anti-CD47 antibody in vivo." (PMID 34858184, 2021). "Moreover, TSP1 released by tumor cells binds CD47 on NK cells inhibiting its activity." (PMID 34447383, 2021). "Given the ability of GEM to increase the expression of the checkpoint CD47 which is involved in blocking the CRT dependent uptake of tumour cells it would be interesting to ascertain whether blocking CD47 expression on PANC-1 cells further enhanced their GEM mediated uptake into APC’s." (PMID 32661823, 2021). "In vivo and in vitro experiments showed that IBI188 could bind to CD47 antigen on the surface of tumor cells and block CD47-SIRPα signal pathway, inhibit the "don't eat me" signal transmitted by CD47, so as to enable macrophages to recognize tumor cells and enable the anti-tumor effect." (PMID 34717705, 2021). "CD47-SIRPα antagonist agents with an intact or even partially inactive Fc portion embedded in their structure may foster anti-tumor activity via antibody opsonization and destruction of target cells through ADCC or antibody-dependent cellular phagocytosis (ADCP)." (PMID 34944850, 2021). "Presently, tumor immune escape is a hallmark of tumor growth and involves tumor expression of inhibitory immune checkpoints or “don’t eat me” signals such as programmed cell death ligand 1 (PD-L1), β2-microglobulin (β2 m), CD24, and CD47 to evade immune responses." (PMID 34827170, 2021). "Although cancer immunotherapy is rapidly advancing, the effectiveness of bsAbs, especially CD47 bsAbs, can vary between different cancer types, different studies, and even different cancer types, in other words, the therapeutic efficacy of anti-CD47 agents may be tumor specific." (PMID 34305918, 2021). "Moreover, Gholamin and colleagues have shown the promising therapeutic potential of targeting the CD47-SIRPα axis in patient-derived orthotopic xenograft models, where it reduces tumor growth in a variety of pediatric brain malignancies and inhibits metastasis." (PMID 34917090, 2021). "Therefore, comparing to traditional cancer immunotherapeutics, bsAbs targets CD47 along with other tumor antigens as a viable strategy for directing the synergistic benefits of combination therapy specifically toward tumor cells, has a potential to enhance security and efficacy." (PMID 34305918, 2021). "However, tumor cells could evade the immune surveillance via utilizing the elevated expression of CD47." (PMID 34068552, 2021). "However, it could also be speculated, that due to CD47's broad expression, a tumor-targeted delivery of the inhibitors could be more suitable." (PMID 34522209, 2021). "Some reports have shown that TAM infiltration is usually positively correlated with SIRPα expression, which might be explained by stimulation of SIRPα expression in macrophages by CD47 self-antigen expressed in tumors, although the extent of this stimulation varies depending on tumor type." (PMID 34573091, 2021). "Notably, CD47 sends “don’t eat me” signals by inhibiting phagocytosis of tumor cells and triggering an immune evasion and therefore serves as a myeloid-specific immune checkpoint when CD47 binds to signal regulatory protein α (SIRPα) that is an inhibitory receptor on macrophages and dendritic cells." (PMID 34305918, 2021). "Moreover, RT, especially multiple rounds or prolonged regimens, can induce adaptive immunosuppression such as upregulation of PD-L1 and CD47 by promoting sustained IFN signaling in tumor cells and production of immunosuppressive cytokine TGF-β (the Yin effects of RT)." (PMID 34830176, 2021).
tumor (continued). "We successfully demonstrated that the time-programmed sequential delivery of sorafenib and aCD47 could reeducate TAMs, reverse immunosuppressive TME, and enhance the CD47-blockade efficacy to inhibit the tumor recurrence, when applied to the surgical beds of mice with resected 4T1 tumors." (PMID 34138357, 2021). "Therefore, in patients with normal or high expression of MHCI on tumor cells, drugs targeting the MHCI/LILRB1 axis may promote anti-tumor immune responses and play a synergistic effect with drugs targeting CD47/ SIRPα axis." (PMID 34625124, 2021). "Furthermore, by using a function-blocking CD47 antibody, it is possible to modulate multiple EV-mediated signals between breast carcinoma cells and endothelial cells that are important for supporting tumor growth and metastasis." (PMID 34830787, 2021). "In addition to checkpoint inhibitors in T cells, immunotherapy now includes inhibition of macrophage’s “Do not eat me” signal on cancer cells, mainly through the interaction of CD47 on the tumor cells with signal-regulatory protein α (SIRPα) on the macrophages." (PMID 33757574, 2021). "The data showed that CD47 might play a tumor activator role in several types of cancer." (PMID 34966389, 2021). "However, even in the absence of macrophages, resident microglia may be transformed into effector cells of tumor cell phagocytosis, in response to anti-CD47 blockade." (PMID 34439159, 2021). "Since DNA damage stimuli could trigger an adaptive antitumor immune response by DNA-sensing cGAS-STING-INF-γ pathway or release of tumor-derived antigens, a rational combined anti-CD47 antibody with chemotherapy or radiotherapy could enhance the efficiency of antitumor immunotherapy." (PMID 34512146, 2021). "Furthermore, its downstream regulator Cdc42 induces tumor metastasis, and thus, both CD47 and Cdc42 may be considered potential therapeutic targets to control NSCLC." (PMID 34367975, 2021). "Furthermore, the binding of CD47 mAbs to CD32a on macrophage can play dual roles: inducing FcγR-mediated phagocytosis of cancer cells and as a scaffold introducing CD47-mediated death signals into tumor cells." (PMID 34717705, 2021). "While therapies targeting SIRPα do not cause direct cytotoxicity on tumor cells, CD47-targeting therapies may induce phagocytosis and direct cytotoxicity of CD47+ cancer cells by engaging activating Fcγ receptors on macrophages and NK cells." (PMID 34572013, 2021). "However, in MM cells engagement of CXCR4 by BoxA does not promote cell growth but rather induces the surface exposure of calreticulin and the depletion of surface CD47, tilting the balance of “eat me” and “don’t eat me” signals, and promoting tumor cell phagocytosis by macrophages." (PMID 33956406, 2021). "Moreover, when meTGCT arrived at the tumor site, high-expressed CD47 could also block the SIRPɑ receptor of the macrophage, thus enhancing the phagocytosis of tumor cells." (PMID 34882297, 2021). "Interestingly, abundant macrophage infiltration was found in CD47-positive tumor tissue." (PMID 34573091, 2021). "Therefore, CD47 is a potential drug target for cancer immunotherapy and anti‐CD47 antibodies were found to effectively release the antiphagocytic signal for macrophages to clear CD47‐expressing tumor cells." (PMID 33629544, 2021). "The most notable characteristic of CD47 is its interaction with macrophages; further studies on anti-CD47 mAb may help explore the role of macrophages in tumor metastasis and the effect of enhancing macrophage phagocytosis for the inhibition of tumor metastasis." (PMID 34367975, 2021). "Because SIRPα from NOD/SCID mice bound human CD47 with an exceptionally higher affinity compared to that from other mouse strains, and even greater than hCD47, this strain is an ideal xenograft model for assessing the tumour inhibitory effect of our antibodies." (PMID 33449453, 2021). "Anti-CD47 antibody treatment could inhibit tumor growth in a pediatric brain malignancies model." (PMID 33251232, 2020).
tumor (continued). "In addition to Sirpα in TAMs, CD47 in tumor cells can also be suppressed by other factors." (PMID 32296015, 2020). "Therapeutics targeting the CD47/SIRPα axis demonstrated anti-tumor efficacy both in vitro and in vivo in preclinical models and are currently being evaluated in clinical trials for both solid and haematologic malignancies as single agents and as combination therapies with tumor-opsonizing mAbs." (PMID 32456204, 2020). "Also, engineered bacteria containing a synchronized lysis circuit (eSLC) to locally release a CD47 antagonist can be used to specifically deliver the agent at the tumor site, to induce a systemic anti-tumor immune response and lyse tumor cells in response to diverse tumor microenvironment stimuli." (PMID 32260071, 2020). "Furthermore, anti-CD47 mAbs prevent or eliminate metastatic lesions and circulating tumor cells." (PMID 32370748, 2020). "A better understanding of the mechanisms that allow tumor cells to avoid immune clearance along with improvements in the delivery of anti-CD47 agents could lead to the development of novel and effective anti-cancer treatments that enhance the phagocytosis of malignant cells." (PMID 32082311, 2020). "It is well accepted that IR can induce immunogenic cell death, resulting in pro-phagocytic signals exposure to the tumor cell membrane (calreticulin, phosphatidylserine and so on), which may be very conducive to enhancing macrophage-dependent phagocytosis of CD47 blockade." (PMID 33020240, 2020). "However, few studies focused on the tumor-intrinsic role of CD47 signals." (PMID 32226539, 2020). "In more aggressive and poorly immunogenic tumors, additional treatment modalities may be necessary to improve tumor control and eradication, such as triple combinations with tumor antigen specific antibodies, CD47/SIRPα antagonists, ICIs, vaccines, or chemotherapy." (PMID 33256806, 2020). "Therefore, in the past years, the study of the “don't eat me” immune checkpoint, namely, the CD47 signaling molecule on macrophages, and the use of inhibitors have provided new ideas for tumor therapy, which may set the basis for a new era of tumor therapy." (PMID 32733941, 2020). "There is growing evidence that the CD47/SIRPα axis may inhibit phagocytosis of tumor cells." (PMID 33552071, 2020). "In addition to CD47, tumor cells also highly express CD24 molecules to achieve immune escape." (PMID 33224886, 2020). "However, CD47/CD20 BsAb treatment showed the maximal inhibition of tumor growth (TGI of 92%), compared with HuNb1-IgG4 or Rituximab treated group (TGI of 76% or 58%), which is in line with the highest phagocytosis showed in the group of CD47/CD20 BsAb treatment." (PMID 31931812, 2020). "Thus, blocking CD47 could enhance anti-tumor innate immunity mediated by macrophages and anti-tumor adaptive immunity indirectly via suppressing immunosuppressive signals in antigen presenting cells and directly via activating T cell cytotoxicity." (PMID 32544882, 2020). "Furthermore, the administration of anti-CD47 antibodies inhibited tumor growth and increased the survival of orthotopic immunodeficient mice transplanted with patient derived GBM cells, providing the first preclinical validation of CD47 as a therapeutic target in GBM." (PMID 33117364, 2020). "The SIRPα-CD47 interaction could be quantitatively measured in live and fixed tumor cells." (PMID 32240171, 2020). "Interestingly, the sequential arm, in which TMZ was given alone in advance followed by TMZ plus anti-CD47 antibody, resulted in significantly improved tumor growth inhibition and survival as compared to monotherapy and concurrent treatment arms in both GL261 and CT-2A models." (PMID 32198351, 2020). "The differential distribution of CD47 and PD-L1 expression within the blood and tissue microenvironments suggests that the peripheral immune response merits further evaluation in parallel to the local response for better understanding the tumor immune reactivity." (PMID 32041353, 2020).
tumor (continued). "An attempt to improve the therapeutic profile and limit potential side effects of anti-CD47 therapy have included two innovations: the use of a nanobody with higher binding affinity than a mAb against CD47, and bacteria engineered to colonise tumours and undergo synchronised lysis." (PMID 32937961, 2020). "Normal cells, especially RBCs with high expression of CD47 might create “antigen sink” that influences the number of anti-CD47 antibodies binding to CD47 expressed on tumor cells and reduces the efficacy of their anti-tumor activities." (PMID 31931812, 2020). "In addition, the display of CD47 molecule enhances macrophage‐mediated tumor cell phagocytosis." (PMID 32999828, 2020). "CD47 binds to a myeloid and neuronal cell receptor called signal regulatory protein α (SIRPα), which initiates a signaling cascade within the bound phagocyte via immunoreceptor tyrosine-based inhibition motifs to inhibit immunoglobulin- or complement-induced efferocytosis of the tumor cell." (PMID 35582455, 2020). "CD47 expression on tumor cells can bind to its counter-receptor signal regulatory protein alpha (SIRPα) on macrophages and produces a “don’t eat me” signal, thus serving as an innate immune checkpoint to inhibit phagocytosis of tumor cells and tumor antigen-presenting to T cells." (PMID 32544882, 2020). "In addition, tumor cells express specific surface proteins such as CD47, PD-L1, MHC-I, and CD24 that prevent macrophages from attacking them and may contribute to metastasis and tumor growth." (PMID 33209523, 2020). "Therefore, our study demonstrated that miR‐708 plays an important tumour suppressor role in BCSCs self‐renewal and chemoresistance, and the miR‐708/CD47 regulatory axis may represent a novel therapeutic mechanism of metformin in BCSCs." (PMID 31273952, 2019). "Since elevated expression of CD47 on tumor cells may promote tumor growth by providing an immune escape mechanism, blocking the CD47 pathway may provide a strategy for driving phagocyte destruction of tumor cells." (PMID 31456686, 2019). "Also, macrophages recognize pro-phagocytic signals, such as calreticulin and phosphatidylserine that are induced on tumor cells as a result of therapies such as chemotherapy and radiotherapy, which in combination with inhibition of the SIRPα/CD47 axis are shown to promote tumor cell uptake." (PMID 31801627, 2019). "In addition, recombinant CD47 proteins blocking the interaction between CD47 and SIRPα may also contribute to the elimination of tumor cells." (PMID 31921125, 2019). "The therapeutic success of anti-SIRPα blocking Abs in tumors SIRPα-positives, might be based on the activation of the ADCP mechanism against tumor cells by macrophages together with the elimination of the phagocytosis blockade exerted by the CD47-SIRPα interaction." (PMID 31921125, 2019). "Furthermore, knockdown of CD47 expression significantly decreased the tumour weights." (PMID 31273952, 2019). "So, while encouraging early responses (i.e. tumor shrinkage by means of macrophage phagocytosis) with anti-CD47 have been observed in patients, longer follow-up is needed to address T-cell activation, since this may be required for durability of clinical responses." (PMID 31801627, 2019). "The CD47/SIRPα axis has been targeted with anti-CD47 blocking antibodies and non-functional engineered SIRPα variants, in combination with anti-tumor therapeutic antibodies such as Rituximab, Cetuximab, and Trastuzumab, displaying synergistic activity in augmenting macrophage phagocytosis." (PMID 31067629, 2019). "Therefore, CD47-blocking strategies could restore the engulfing and tumor-antigen-presenting activities of M1-like TAMs and thus enhance the priming of effective CD8+ T cells." (PMID 31771653, 2019). "Moreover, CD47 is highly expressed on the cancer cell surface in many tumor types." (PMID 31629410, 2019).
tumor (continued). "Using scRNA-seq, we showed that anti-CD47 treatment significantly remodeled the intratumoral lymphocyte and macrophage compartments in Panc02 tumor-bearing mice by increasing the pro-inflammatory macrophages that exhibit anti-tumor function, while reducing the anti-inflammatory macrophages." (PMID 31771616, 2019). "Additionally, the use of inactivated non-replicating tumor cells as vaccines utilizes the immunogenic potential of whole tumor cells leading us to hypothesize that cell-surface CD47 depletion can unmask whole-cell vaccines to the immune system effectively." (PMID 31882679, 2019). "Tumor‐bearing mice treated with CD47 mAb plus doxorubicin combination therapy demonstrated significantly reduced tumor size and prolonged survival compared to control groups that received CD47 mAb (P = 0.03), doxorubicin monotherapy (P = 0.01), and control IgG (P = 0.001)." (PMID 31376208, 2019). "CD47, also known as the “don’t eat me” signal, is expressed on normal cells to prevent macrophage engulfment but is often overexpressed on malignant cells to engage its receptor SIRPα found on anti-tumor macrophages and neutrophils in order to prevent phagocytic function." (PMID 30621125, 2019). "Furthermore, tumour cell-bound CD47 is important for THBS1 activity in tumour cell invasion." (PMID 30850588, 2019). "To focus CD47 blockade on tumor cells, we generated two bispecific antibodies (biAbs) pairing a high affinity arm targeting a tumor associated antigen (TAA), i.e., CD19 or mesothelin (MSLN), to an optimized lower affinity arm targeting CD47 and investigated their efficacy in xenograft tumor models." (PMID 30400822, 2018). "Furthermore, when activated human dendritic cells or macrophages were co-cultured with CD47 positive human tumor cells, SIRPα - Fc-CD40L was shown to enhance phagocytosis of human tumor cells, and in vivo in mice, induced rapid activation of CD4+ and CD8+ dendritic cells." (PMID 30400822, 2018). "Some studies showed that anti-CD47 antibodies might directly induce the apoptosis of tumor cells." (PMID 30525058, 2018). "It remains unclear why B6H12 in solution exhibit slower kinetics compared to soluble CC2C6, however, having two different monoclonal antibodies able to induce cell death in a CD47-dependent manner affirms the strategy of targeting CD47 as an anti-tumour therapy." (PMID 29748606, 2018). "The result showed that cells incubated with mSIRPαext exhibited significantly higher fluorescence intensity as compared with the control cells, suggesting that the mSIRPαext fusion protein could bind to L1210 tumor cells most likely through the interaction with CD47." (PMID 30105024, 2018). "However, CD47 negatively regulates the function of the human T cell, dendritic cell, NK cell, and B cell and plays an inhibitory role in the immune response against tumor cells." (PMID 30525058, 2018). "Thus, innate checkpoint inhibition may enhance the anti-tumor effect of DNA damaging agents.CD47 is an immune checkpoint that binds signal regulatory protein alpha (SIRPα) and delivers a “do not eat” signal to suppress macrophage phagocytosis." (PMID 30400835, 2018). "Hence, CAR-T cell therapy combined with CD47 inhibition could improve tumor elimination by enhancing the immune system." (PMID 29329591, 2018). "Depletion of NK cells similarly attenuated the anti-tumor activity of a SIRPα blocking antibody in a syngeneic murine renal carcinoma model, but the same antibody did not inhibit NK killing of the tumor cells in vitro, further supporting a SIRPα-independent function of CD47 in NK cells." (PMID 30643501, 2018). "Moreover, FusOn-CD47-Luc seems to stay in the tumor tissues substantially longer than FusOn-Luc." (PMID 30349648, 2018). "Therefore, CD47 is a potential therapeutic target for tumor therapy." (PMID 28290053, 2018). "Thus, how to block CD47-SIRPα inside the tumor tissues specifically becomes the challenge." (PMID 28077173, 2017).